MYC (MYC proto-oncogene, bHLH transcription factor)
Diseases named in the same sentence as MYC in open-access papers (continued):
Sharing a sentence is not in itself a finding about the gene and the disease.
cancer (continued). "The role of MYC in various cancers and its function in transcriptional regulation of ribosome biogenesis are well characterized." (PMID 40524273, 2025). "The avian myelocytomatosis viral oncogene homolog (MYC/MYC) is one of the most frequently mutated oncogenes, and its overexpression is strongly associated with cancer, making it a major focus of research." (PMID 39858030, 2025). "Overall, these data support the important role of SMYD3-dependent c-MYC methylation in cancer stemness." (PMID 40588481, 2025). "rLon treatment was previously shown to inhibit MYC expression and reduce MYC protein levels in vivo, resulting in protection in two murine cancer models." (PMID 40000737, 2025). "MYC is a key oncogenic driver in PCa, and activation of MYC signaling promotes cancer growth and invasion." (PMID 40427108, 2025). "BRD4 is a positive regulator of the MYC oncogene, the expression of which is deregulated in many cancers, and accumulating evidence supports the involvement of BRD4 in the progression of many malignancies." (PMID 41311847, 2025). "A recent study has shown ribosomal biogenesis can be suppressed by inhibiting the rDNA using a small molecule CX-5461, which has the capacity to control or kill the MYC-driven cancer cells." (PMID 39779613, 2025). "MYC is among the most frequently activated oncogenes in human cancers as it enhances cell proliferation in part through increasing the cell’s protein synthetic capacity." (PMID 40524273, 2025). "Recently, a study showed that eIF5A regulates the selection of MYC-mRNA start codon in cancer cells." (PMID 39779613, 2025). "Together, these findings provide a rationale for exploring combinations of MYC inhibitors with DNA-PKcsi as a strategy to simultaneously suppress oncogenic signalling and the compensatory DNA repair pathways that support cancer cell survival." (PMID 41561634, 2025). "In line with its central role in proliferation, deregulation of c-MYC is a common characteristic across a broad spectrum of human cancers." (PMID 40406608, 2025). "The most common genetic alteration of the MYC gene across various cancers is its amplification, which leads to elevated MYC protein levels, resulting in abnormal activity and, ultimately, cancer development." (PMID 39858030, 2025). "In both species, new transcripts were canonically spliced, and expression predicted embryonic processes and regulatory transcription factors (TFs) associated with cancer, including MYC/c-Myc." (PMID 40809689, 2025). "Our recent study established a DOX‐inducible MYC‐mutant‐MYC‐KO system in cancer cell line, which enables the accurate profiling of transcriptional consequences of MYC's loss‐of‐function (LOF) on its RNA and DNA binding ability." (PMID 41025936, 2025). "The MYC is overexpressed in a variety of human cancers through amplification, insertion, and rearrangements." (PMID 40949131, 2025). "Our study thus identifies a key mechanism by which rearrangements at the PVT1 locus activate additional oncogenic pathways that synergize with MYC to exacerbate the aggressiveness of MYC+ cancers." (PMID 40027648, 2025). "Since MYC is one of the most frequently altered driver genes involved in cancer formation, it is a potential target for new anti-cancer therapies." (PMID 39875774, 2025). "Dysregulated lipid metabolism is widely documented in benign and malignant neoplasms, and MYC, in collaboration with sterol regulated element-binding protein (SREBP), has been shown to regulate lipogenesis in the promotion of tumorigenesis." (PMID 40422212, 2025). "MYC participates in cell proliferation, metabolism, differentiation, apoptosis, and other processes, and has an important function in many types of cancer." (PMID 40944417, 2025).
cancer (continued). "Further studies that detail the contribution of MYC to CBSI response would be very informative to the ~50% of cancers that overexpress this major oncogene." (PMID 40430358, 2025). "Researchers are developing JAK2 inhibitors (such as ruxolitinib), STAT3 inhibitors, and MYC inhibitors as new treatment options for cancer patients." (PMID 40944417, 2025). "This dependency has significant therapeutic implications: studies have demonstrated that SWI/SNF-deficient cancers, including MRT, are particularly sensitive to MYC inhibition." (PMID 40076599, 2025). "This discovery is notably important due to the documented function of c-MYC as a promoter of oncogenesis in various cancer types." (PMID 40711670, 2025). "Increasing evidence suggests that targeting upstream regulatory factors such as histone deacetylase (HDAC), phosphoinositol 3-kinase (PI3K), polo-like kinase 1 (PLK1) and BET bromodomain can lower MYC protein levels and inhibit MYC-driven cancer growth." (PMID 40229260, 2025). "These include FLT3 in FLT3-ITD positive cells, DOT1L in PICALM-MLLT10, and the oncogene c-MYC, which is overactive in most cancer types." (PMID 40082888, 2025). "Overall, these findings suggest that squamocin is less neurotoxic than rotenone and represents an attractive candidate for targeting EZH2/MYC axis‐dependent cancers." (PMID 39823459, 2025). "The discovery of MYC amplification/overexpression as a major G3 MB pathogenic factor aligns with estimates of aberrant MYC activity in 70% of human cancers." (PMID 41198629, 2025). "This study adds to a growing body of evidence implicating MYC in the regulation of splicing factors in cancer." (PMID 41101775, 2025). "Studies have shown that the activation of MYC signaling enables cancer cells to disrupt the surrounding microenvironment, allowing them to evade the body’s immune response." (PMID 40492126, 2025). "In cancer cells, MYC plays a substantial role in promoting the transcription of the L-type amino acid transporter (LAT) (Na+-independent transporters), which transports neutral AAs into cells." (PMID 41008653, 2025). "Strategies to inhibit MYC function by targeting mRNA translation hold potential for therapeutics utility in Myc-dependent cancers." (PMID 40943063, 2025). "Recently, we proposed that a common mechanistic theme underlying the etiology of SWI/SNF-altered cancers involves interactions between SWI/SNF and oncoprotein transcription factors, one of them being MYC." (PMID 40647552, 2025). "MYC deregulation is pervasive, occurring in over 70% of human cancers and correlating with poor prognosis, making the hyperactivated MYC oncoprotein an appealing yet challenging target for drug development due to its “undruggable” characteristics." (PMID 39592836, 2025). "In this review, we delineate the multifaceted roles of MYC in cancer progression, highlighting a spectrum of therapeutic strategies and inhibitors for cancer therapy that target MYC, either directly or indirectly." (PMID 40290126, 2025). "MYC proteins, including MYCN, c-MYC, and MYCL, play a critical role in tumorigenesis and are implicated in 70% of human cancers." (PMID 40552293, 2025). "Currently, however, our understanding of how MYC features in SWI/SNF-altered cancers has been limited to SNF5-null cancer cells." (PMID 40647552, 2025). "The MYC-gLINC axis therefore shows a mechanism by which cancer cells sustain cell survival during serine deprivation through enhancing glycolysis and sustaining ATP production." (PMID 40126351, 2025). "A Journal of Hematology & Oncology review demonstrates how MYC functions in cancer development while establishing its potential value as a therapeutic target." (PMID 40959208, 2025). "For instance, MYC is frequently upregulated in cancers through copy number alterations, whereas its developmental expression is tightly regulated by genome architecture and epigenetic mechanisms." (PMID 41101775, 2025).
cancer (continued). "MYC is overexpressed in most types of cancer and promotes oncogene transcription by binding to active promoters." (PMID 40032852, 2025). "Our findings align with studies in other cancer types showing that IGF2BPs stabilize oncogenic mRNAs, such as MYC and SRF." (PMID 40918643, 2025). "Hyperactive MYC promotes inflammation and cancer transformation by inhibiting the negative regulation of Splicing Factor SRSF1 in AP." (PMID 40699778, 2025). "The oncogene MYC, a principal regulator of cell proliferation, is dysregulated across a broad spectrum of cancer types." (PMID 40032852, 2025). "MYC sensitizes cancer cells to mitotic blockers by upregulating pro-apoptotic proteins and suppressing anti-apoptotic proteins." (PMID 39688743, 2025). "In human cancers, there exists a proto-oncogene named MYC, which can affect the expression of several genes and regulate cell proliferation under normal conditions." (PMID 39852139, 2025). "ZFHX3 is a transcription factor and negative regulator of c-Myb that has been previously reported as gained in canine OS, and has been shown to be altered in a mutually exclusive manner with MYC in human cancers." (PMID 40493617, 2025). "Our results revealed significant differences in the distribution of malignant cells across the CAF subpopulations, with distinct heterogeneity in the activity levels of specific pro-cancer signaling pathways, such as MYC, WNT, TGF-β, and PI3K." (PMID 40589759, 2025). "Analysis revealed that genes (or proteins) in the connected subnetworks interact with KRAS, MYC, and NTRK1, all of which are well-known cancer-associated genes (proteins), respectively." (PMID 40662800, 2025). "Although translation-related genes are already among the highly expressed genes, MYC overexpression in cancer further increases their expression, leading to the suggestion that MYC functions as a “transcriptional amplifier”." (PMID 40524273, 2025). "MYC is a proto-oncogene that is frequently studied in cancer research, also at the single-cell level, making it a clinically relevant target for gDNA isolation." (PMID 40596037, 2025). "Consistent with its role in preventing exon skipping in MYC-driven cancers, PRMT5 likely promotes SRSF1 recruitment to Tip60 pre-mRNA to support splicing of full-length, catalytically active Tip60." (PMID 40846633, 2025). "Future efforts should aim to validate top novel candidate compounds and combinations in vitro, particularly in MYC‐addicted cancer cell lines." (PMID 41025936, 2025). "We found that CPSF1 amplification co-occurs with MYC amplification in both patients and cancer cell lines." (PMID 41463412, 2025). "Although miR-34c has been extensively investigated within the realm of cancer, particularly concerning its regulatory function on the MYC proto-oncogene, its precise impact on the MYC gene in the context of brain damage remains insufficiently documented." (PMID 39129166, 2025). "Our study builds on this emerging evidence and further supports PA2G4 as an oncogenic cofactor in MYC-driven cancers." (PMID 41002386, 2025). "Given the universal involvement of the EZH2/MYC axis in tumorigenesis, this class of inhibitors has the potential to accelerate the development of therapeutics targeting cancers driven by the EZH2/ MYC axis." (PMID 39823459, 2025).
cancer (continued). "Dysregulation of MYC results in the reprogramming of signaling pathways in cancer cells, providing them with selective advantages." (PMID 39592836, 2025). "The observed downregulation of critical oncogenes such as KRAS, NRAS and MYC further highlights the potential of this combination therapy to target multiple oncogenic pathways, reducing the likelihood of cancer cell survival and proliferation." (PMID 40307570, 2025). "In the near future, modulators of the EGFR/RAS/MYC axis are likely to become effective therapeutic tools for treating cancer, particularly in cases where existing therapies are unsuccessful." (PMID 39858030, 2025). "While the pivotal role of c-MYC in cancer metabolic alterations has been firmly established, the mechanistic events governing its aberrant activity have not been fully explored." (PMID 40114244, 2025). "Strategic integration and rational combination therapies represent essential future directions in MYC-targeted cancer treatment." (PMID 40365020, 2025). "The MYC oncogene is deregulated in more than 50% of human cancers, including both adult and pediatric malignancies." (PMID 41002386, 2025). "MYC has been suggested to act as a general amplifier of RNA production, potentially overwhelming the splicing machinery in MYC-driven cancer cells because of excessive total RNA output." (PMID 40846633, 2025). "Compounds that target the MYC/MAX interaction have some effect in cancer, though these inhibitors often suffer from limited potency and significant off-target effects." (PMID 41002386, 2025). "Due to these factors, MYC is considered a highly attractive target for cancer treatment and is prioritized in the search for effective cancer therapies." (PMID 40076599, 2025). "This loss of p21-mediated regulation promotes unchecked cell cycle progression and is frequently observed in MYC-driven cancers." (PMID 40076599, 2025). "This aligns with previous findings showing that GHRH antagonists lower MYC expression in various experimental cancer models, including when combined with chemotherapy." (PMID 40244089, 2025). "MYC is dysregulated in many cancers, including T-ALL where it promotes expression of multiple genes involved in metabolism, protein synthesis and proliferation." (PMID 40319015, 2025). "SF3B1 mutation accelerates cancer progression through alternative RNA splicing in various cancer types by activating the Akt and NF-κB pathway, MYC activation, inflammation pathway, and TGF-β signaling in several cancers." (PMID 40694421, 2025). "These cancer cells are typically characterized by a quiescent state with suppressed activity of MYC and MTOR." (PMID 41090785, 2025). "MYC is a vital oncogene and usually, its high expression in cancer is closely related to tumorigenesis." (PMID 40584294, 2025). "At the MYC locus (chr8:127–130 Mb), which is subject to cell type–specific enhancer regulation across cancers, H3K27ac HiChIP revealed extensive E-P interactions in control cells linking MYC to PVT1 and CCDC26." (PMID 41509392, 2025). "The expression of MHC-I, β2M, and other APM components in cancer has been shown to be influenced by a number of oncogenic pathways, including the c-MYC, n-MYC, HER2, MAPK, and EGFR." (PMID 40098955, 2025). "We propose that FFX orchestrates AUF1’s inner membrane recruitment, facilitating activation of AKT signaling, and thereby mTORC1 and MYC in MYC+ cancer." (PMID 40027648, 2025). "G-quadruplexes regulate gene expression, including 90% of MYC expression, thereby making them potential drug targets for MYC addictive cancers." (PMID 40290126, 2025). "Targeting MYC, either alone or in conjunction with immunotherapy, is anticipated to offer a curative approach for a majority of cancers." (PMID 40732268, 2025). "This review explores the complex mechanisms by which TERT modulates key signaling pathways, such as NF-κB, AKT, and MYC, highlighting its role in driving autonomous cancer cell growth and resistance to therapy in B-cell malignancies." (PMID 40227701, 2025).
cancer (continued). "These widespread implications underscore the urgent need for effective MYC-targeting strategies across multiple cancer types." (PMID 40365020, 2025). "c‐MYC, an additional critical transcription factor that is frequently overexpressed in various cancers, is instrumental in enhancing glycolysis to meet the elevated energy requirements and swift replication of neoplastic cells." (PMID 39993964, 2025). "Our approach provides new insights on utilizing existing anticancer drugs to indirectly target MYC in MYC‐driven cancer." (PMID 41025936, 2025). "The effectiveness and synergistic behavior of the combination therapy was also seen in KRASG12V/MYC cancer cells grown as three-dimensional colonies." (PMID 40550880, 2025). "The inhibitors significantly downregulated the expression of MYC, which, in addition to its tumorigenesis‐promoting activity, also enables cancer cells to evade anti‐cancer immune responses." (PMID 40285526, 2025). "In fact, when MYC is inhibited, cancer cells lose both their proficient DNA repair capacity and their protective mechanisms against replication stress." (PMID 41561634, 2025). "We show why the cell-autonomous and immune evasive functions of MYC are mutually dependent and discuss ways to target MYC proteins in cancer therapy." (PMID 38957016, 2024). "Nevertheless, considerable progress has recently been made in the development of KRAS and MYC inhibitors for the treatment of cancer starting to show promising clinical results, likely bringing the perception of these oncogenes as “undruggable” to an end." (PMID 39164274, 2024). "HPV 16/18 E6/E7 activates IGF2BP2 and regulates MYC methylation to facilitate aerobic glycolysis and cancer progression in CC." (PMID 38721006, 2024). "Exosomal miR-105 from cancer cells reprogram CAF metabolism to support cancer growth by conditioning the shared metabolic environment in an MYC-dependent manner." (PMID 38495881, 2024). "The MYC oncogenic pathway is frequently deregulated in diverse cancers, and thus stands as a prominent therapeutic target." (PMID 39093942, 2024). "We also spiked in a panel of 41 negative control sgRNAs (targeting nonhuman genes such as Luc, LacZ, Ren and Rosa26 and scrambled sequences) and 27 positive control sgRNAs (targeting cancer-essential genes such as MYC, PCNA and RPA3)." (PMID 38316881, 2024). "Conversely, IL6R and MYC KO cells displayed a significant reduction in both number and size of spheres compared to SC cells (IL6R KO, p ≤ 0.001; MYC KO, p ≤ 0.01), suggesting reduced cancer malignancy." (PMID 38607055, 2024). "First, by blocking phosphorylation of Ser2-RNAPII, CDKI-73 inhibits transcription and reduces levels of key cancer-promoting factors such as MYC, pro-survival members of the BCL-2 family, and AR." (PMID 39117800, 2024). "Of these, a significant number of cancer-related pathways, particularly MYC-target pathways, were downregulated by MP1." (PMID 38200580, 2024). "Adaptation to hypoxia has been found to typically lead to HIF‐1α overexpression and mediate Gln catabolism through the downregulation of MYC expression in diverse cancer types, including glioma, CC, EC, BC, and ovarian cancer." (PMID 38721006, 2024). "Knockdown of c-MYC can inhibit the transcription of ribosomal proteins, presenting opportunities for designing new targeted cancer treatments." (PMID 38918775, 2024). "Bromodomain and extra-terminal domain (BET) proteins, which function partly through MYC proto-oncogene (MYC), are critical epigenetic readers and emerging therapeutic targets in cancer." (PMID 39872506, 2024). "EXOSC5 knockdown diminished EC-CSC self-renewal and reduced expression of key cancer stemness proteins, including c-MYC and SOX2." (PMID 38164180, 2024). "In some cancer cells with mutated KRAS it was found that its suppression causes polyubiquitination and proteasomal degradation of the MYC protein." (PMID 39457457, 2024).